STAT3 (signal transducer and activator of transcription 3)
Diseases named in the same sentence as STAT3 in open-access papers (continued):
Sharing a sentence is not in itself a finding about the gene and the disease.
tumor (continued). "In murine CD8+ T-cells, STAT3 has been shown to inhibit both IFN-γ-mediated CXCL10 production by myeloid cells and CD8+ T-cells CXCR3 expression (the receptor of CXCL10), blocking the migration of these cells to the tumor site." (PMID 31480382, 2019). "Mice without STAT3 in myeloid compartment of tumor stroma, including DCs and macrophages, present reduced numbers of tumor-infiltrating CD4+CD25+/FOXP3+/LAG3+ Tregs, along with an increase in CD8+ effector T-cells." (PMID 31480382, 2019). "Similarly, in tumor tissues of CMS-induced mice, the expression and phosphorylation of ABL1, p-NF-κB1, p-STAT3, IL-6, IL-1β, and COX2 significantly increased." (PMID 31396300, 2019). "Aberrant JAK/STAT signaling has been identified as a strong oncogenic factor involved in tumor growth, invasion, and metastasis; thus, potent JAK2 and STAT3 inhibitors have been developed and are currently in different stages of preclinical and clinical investigations." (PMID 31511084, 2019). "In parallel, knockdown of PTEN alone with normal STAT3 expression displayed significantly reduced tumorigenic potential, indicating that STAT3 serves as a tumor suppressor in the absence of PTEN." (PMID 31847229, 2019). "Therefore, our findings and those of previous studies suggest that GAS5 knockdown-induced G1/S progression occurs via STAT3-mediated signaling pathways, and further suggest that reduced GAS5 expression contributes to tumor progression in MM patients." (PMID 30569211, 2019). "A tumor suppressor microRNA, miR-22, is inhibited in CTCL cell lines by STAT5B, STAT3, and JAK3." (PMID 31684088, 2019). "Accumulating evidence indicates that these tolerogenic properties are highly regulated by the constitutive and persistent activation of the oncogenic signal transducer and activator of transcription 3 (STAT3) protein, which impairs anti-tumor immunity and enhances tumor progression." (PMID 31698775, 2019). "Moreover, STAT3 inactivation reversed the glycolytic shift by down-regulating key enzymes (including PDK) and then inhibited tumor growth." (PMID 31506552, 2019). "In addition to EGF, IL-6 is another oncogenic cytokine, and its activation can induce STAT3 and AKT signaling, resulting in tumor growth and invasion in numerous cancers, including cervical." (PMID 31235851, 2019). "Constitutive activation of STAT3 and STAT5 is involved in tumor formation and progression." (PMID 31569642, 2019). "Taken together, our results then raise the intriguing notion that the reciprocal regulation of tumor TGF-β and 4-1BB costimulation may determine the efficacy of anti-4-1BB therapy in part through STAT3-mediated CD73 expression on effector T cells." (PMID 30635578, 2019). "On the other hand, specific deletion of Stat3 in differentiated NK cells, using Ncr1iCre Stat3fl/fl mice, leads to an increased expression of DNAM-1, Perforin, and Granzyme B, and enhanced anti-tumor activity, as the result of the possible repressive functions of STAT3 on these cells." (PMID 31681330, 2019). "Taken together, LINC81507 is decreased in NSCLC and functions as a sponge to miR-199b-5p to regulate CAV1/STAT3 pathway, which suggests that LINC81507 serve as a tumor suppressor and potential therapeutic target and biomarker for metastasis and prognosis in NSCLC." (PMID 31296840, 2019). "Therefore, by blocking the expression of STAT3, it is possible to reeducate TAM from tumour-promoting to tumour-inhibiting macrophages." (PMID 30931335, 2019). "This study was undertaken to investigate whether progranulin sustains STAT3 hyper‐activation in CRC and whether its inhibition may represent a feasible approach to restrain STAT3 oncogenic function in such neoplasia." (PMID 31361391, 2019). "We recently identified RhoU as a STAT3 target gene downstream of gp130 cytokines, and reported a positive correlation between STAT3 activation and RHOU expression levels in a panel of human tumor cell lines, including MDA-MB-231 cells." (PMID 30654518, 2019).
tumor (continued). "Moreover, simultaneous admission of STAT3 and HIF-1α inhibitors significantly increased the anti-tumor activity of cisplatin in TNBC under hypoxic conditions." (PMID 31443516, 2019). "As shown, correlating the inferred STAT3 activities with tumor purity revealed that STAT3 activity inferences did not reflect tumor purity." (PMID 31796877, 2019). "As STAT3 signaling plays a pivotal role in the regulation of the cancer stromal and immune cells of the tumor microenvironment, the possible use of progranulin ASO in the clinic should take into account issues related to the modulation of STAT3 in such cell compartments." (PMID 31361391, 2019). "This network demonstrates that 61 exosomal molecules may affect tumor progression through pathways controlled by key components including MET, Ras, RAF1, Mek, ERK1/2, MITF, BCL2, PI3K, Akt, mTOR, PD-1, KIT, JAK STAT3, or ETS1." (PMID 31681332, 2019). "Therefore, the therapeutic use of STAT/JAK-modulators should be carefully evaluated for their specific targeting of STAT3 activity while preserving IFNγ-induced STAT1/2 signaling, which appears to be beneficial for anti-tumor immune responses." (PMID 31766350, 2019). "Signal transducer and activator of transcription 3 (STAT3) is a transcription factor that is overexpressed and/or hyperactivated in multiple human cancers, where it enhances tumor cell survival and invasion through transcription of anti-apoptotic and pro-proliferative genes." (PMID 31671769, 2019). "This may be due to this fact that STAT3 and STAT1 proteins are involved in the progression of several tumor cells." (PMID 31569687, 2019). "Concerted regulation of STAT3 and STAT5 activation in CD8 T effector and memory cells has been shown to impact their tumor-specific responses including intra-tumor accumulation, long-term survival, cytotoxic activity and resistance toward tumor-derived immune suppression." (PMID 31766350, 2019). "Therefore, TGF-β-dependent fine-tuning of 4-1BB signaling contributes to “regulatory” CD73+CD8+ T cell responses via two different aspects: (i) the signal intensity of the STAT3 pathway and (ii) the levels of IFN-γ and IL-2 production in the tumor." (PMID 30635578, 2019). "Also, STAT3 induces the expression of IL-10 and TGF-β1, through direct promoter binding, which ultimately restrains the tumor-suppressive role of CD8+ effector T-cell function and dendritic cells." (PMID 31861720, 2019). "Similar to our earlier findings, STAT3 expression was inversely correlated with tumor purity at the primary site and was also negatively correlated at metastatic lesions from liver, whereas it was trending to be significant in lung and lymph node." (PMID 31796877, 2019). "Signal transducer and activator of transcription 3 (STAT3) pathway is also activated as a major cell survival mechanism in HCC but not in the surrounding non-tumor tissue or normal liver." (PMID 31547152, 2019). "By modulating the level of STAT3 expression on human UBC cell lines, we could demonstrate a relevant role for STAT3 in tumor cell viability, proliferation and invasion." (PMID 31438567, 2019). "Moreover, we found that KIF20A achieved its pro-tumor function by activating the JAK/signal transducer and activator of transcription 3 (STAT3) signaling pathway." (PMID 31841120, 2019). "EGFR overactivation may result in the resistance of tumor cells to chemotherapy and radiation treatment, via the activation of the PI3K/Akt, JAK/STAT3 and Ras/Raf/MEK/Erk downstream signaling pathways." (PMID 30947731, 2019). "This phenotype would have mesenchymal features, that would result as a downstream effect of the STAT3-RAS-MAPK-ERK-MYC pathway, regulating ID3/E47 interactions and promoting tumor cell migration and invasion through expression of mesenchymal genes such as MMPs, SNAIL1, TWIST1, and PRRX1." (PMID 30899759, 2019).
tumor (continued). "Using a tumour xenograft model and primary cisplatin-resistant and -sensitive cells, HO-3867 selectively targets STAT3 leading to apoptosis only in the cancerous cells without affecting the non-cancerous cells." (PMID 31766284, 2019). "JAK1/2 inhibition in tumor cells of ruxolitinib treated mice was efficient, since activation of the downstream effector STAT3 was almost absent after tyrosine kinase inhibitor treatment." (PMID 31407334, 2019). "Overexpression of PIM1 correlates with overexpression of STAT3 in ATLL patient samples, and treatment of ATLL cell lines with a Pim1 inhibitor, AZD1208, led to decreased proliferation, while treatment of ATLL mice with AZD1208 led to decreased tumor formation." (PMID 31684088, 2019). "The anti-tumor effect of GJXLT might be related to the inhibition of p-STATS and VEGF expression in the JAK2/STAT3 pathway." (PMID 30271456, 2018). "In addition, immunoblot analyses exhibited an elevated activation of STAT3 (phosphorylation at Y-705), an established key driver of UVB-induced SCC development, in tumor samples from both, AHR+/+ and AHR−/− mice, as compared to irradiated non-lesional skin." (PMID 30013037, 2018). "We next investigated whether combinatorial blocking of IL-6/STAT3 and PI3K/Akt pathways would have an effect on tumor growth and response to chemotherapy." (PMID 29930760, 2018). "Moreover, the expression of SOCS3 and phosphorylated STAT3 and AMPK was increased, and the expression of phosphorylated 4E-BP1 was decreased in the gastrocnemius muscle of tumor-bearing mice." (PMID 30555329, 2018). "Studies report that S1PR1 induces persistent activation of STAT3, and STAT3, a transcription factor for S1PR1, induces S1PR1 expression in a positive feedback loop for maintaining persistent STAT3 activation in tumor cells and the tumor microenvironment for malignant progression." (PMID 30377291, 2018). "Src can increase pro-inflammatory cytokines production for tumor development and activate survival effectors for chemoresistance, including TNF-α, IL-1β, IL6, phosphoinositide 3-kinases (PI3Ks), AKT and STAT3." (PMID 30473665, 2018). "Additionally, inactivation of STAT3 in intracranial GL261 tumors by siRNA resulted in GAM activation and tumor growth inhibition." (PMID 29389898, 2018). "The expansion of MDSCs in the tumor microenvironment is induced by cancer-derived cytokines and growth factors, including IL-6, IL-10, VEGF, hepatocyte growth factor (HGF) or G-CSF, which share ability to induce STAT3 signaling." (PMID 29921770, 2018). "These genes likely function as downstream effectors of STAT3 in GBM to regulate not only cell proliferation (e.g., GAS7, IGFBP2, MEOX2 and MXI1), and but also tumor-stroma interactions by modulating protein secretion (e.g., ANXA1, ARL4C, EMILIN1, EMP2, EXTL3 and PDIA4)." (PMID 29774125, 2018). "An investigation performed in two transplantable and two transgenic tumor murine models has shown that the tumor-induced hypoxia triggers the upregulation of CD45 tyrosine phosphatase activity in TME residing MDSCs, resulting in downregulation of STAT3 and differentiation of MDSCs into TAMs." (PMID 29675018, 2018). "Because HDAC3 is a critical regulator of STAT3 signaling during liver regeneration, we investigated whether elevated HDAC3 in HCC was correlated with a higher tumor cell proliferation rate." (PMID 29540666, 2018). "In this study, we show that local tumor cell density in 3D collagen I matrices regulates the expression and activity of MMPs through the synergistic paracrine signaling mechanism between IL-6 and IL-8 via the JAK2/STAT3 pathway." (PMID 30220965, 2018). "Given that the phosphorylated STAT3 acts as a transcription factor by translocating to the nucleus to activate genes involved in tumour angiogenesis, we detected whether SIRT2 mediates the phosphorylation of STAT3 in the nucleus." (PMID 30584257, 2018).
tumor (continued). "Further experiments indicated that ERO1α promoted tumor angiogenesis and positively correlated with VEGF-A expression via the S1PR1/STAT3/VEGF-A pathway, suggesting that ERO1α may be a novel therapeutic target for inhibiting tumor angiogenesis." (PMID 30377291, 2018). "It exerted the anti-tumor effect through the NF-κB, STAT1 and STAT3 signal pathways, which could re-direct the type of TAMs both in vitro and in vivo." (PMID 30513582, 2018). "Signal transducer and activator of transcription 3 (STAT3) functions as a signal messenger and transcription factor, which regulates the transcription of downstream target genes during malignant transformation and tumor development." (PMID 29843746, 2018). "Additionally, local tumor cell density regulates cell density-dependent phenotypes through the synergistic signaling of IL-6 and IL-8 via the JAK2/STAT3 pathway." (PMID 30220965, 2018). "Compared with the paired non-tumor liver tissues, significant up-regulation of CCRK, p-GSK3βSer9/GSK3β, p-mTORSer2448/mTOR, p-4E-BP1Thr37/46/4E-BP1, p-S6KThr389/S6K, mSREBP1, G-CSF, p-STAT3Tyr705/STAT3, and AR were detected in HCC tissues (p < 0.05)." (PMID 30523261, 2018). "IL-17-dependent STAT3/GIV signaling pathway is responsible for VEGF release from cancer cells and promotion of tumor angiogenesis, and GIV expression positively correlates with IL-17+ cell presence and increased microvessel densities and predicts poor survival of NSCLC patients." (PMID 29675018, 2018). "In addition, we also found that a STAT3 inhibitor (WP1066) prevented STAT3 Y705 phosphorylation and attenuated GIC-driven tumor growth." (PMID 29774125, 2018). "Furthermore, myricitrin has been shown to attenuate tumour promoting-induced activation of c-fos and activator protein-1, and to inhibit JAK1/STAT3 pathways." (PMID 29523111, 2018). "MiR-203 as a tumor suppress gene, studies have found hepatic over-expression of miR-203 could facilitate the initiation of the liver by targeting SOCS3 through IL-6/STAT3 signaling pathway." (PMID 29670525, 2018). "Furthermore, STAT3 knockdown significantly reduced the cell viability of the HT29 cells and tumor growth in tumor xenografts." (PMID 30068339, 2018). "In our study, we established GBM-derived irradiated/invasive cells (R2I2) as radioresistant GBM cell lines and hypothesized a novel relationship between STAT3 and Slug expression in R2I2 cells to regulate CSC properties, tumor invasion, and radioresistance." (PMID 30551687, 2018). "Interestingly, we showed that a small molecule inhibitor of STAT3 blocked HCC tumor growth, reduced tumor development, and improved NASH in HepPten- mice, and that these effects were associated with an inhibition of TLR signaling pathways." (PMID 30034633, 2018). "In this study, DLD-1R and HCT-116R cells appeared to be sensitive towards regorafenib treatment as demonstrated by the decreased number of colonies, tumor spheres and stem-like phenotypes (tumor spheres and side-populations) and markers (WNT1, mTOR/STAT3, Notch1)." (PMID 30005681, 2018). "STAT3 proteins have been reported to downregulate expression of the vascular endothelial growth factor (VEGF), thereby reducing angiogenesis and delaying progress of the tumor." (PMID 29794990, 2018). "Altogether, STAT3 and its downstream target genes not only promote proliferation (Cyclin D1, c-Myc), survival (Bcl-2, survivin, Bcl-xL), angiogenesis (VEGF, HIF1α), and metastasis (MMPs), but also inhibit anti-tumor immune responses." (PMID 30217007, 2018). "Thus, our results not only integrate inflammation with epigenetic regulation in TNBC, but also suggest crosstalk between STAT3 and NF-κB in SMYD2 mediated tumor progression." (PMID 29487338, 2018). "Despite this discrepancy, the negative effect of STAT3 activation on the expression of MHC class II and costimulatory molecules, such as CD80 or CD86, is well established by studies in tumor-associated DCs and other antigen presenting cells (APCs)." (PMID 29921770, 2018).
tumor (continued). "One of the most peculiar features of STAT3 is that it can act both in cell-autonomous and non-cell-autonomous manners, simultaneously modulating the phenotypes of the tumor cells and their microenvironment." (PMID 30231553, 2018). "STAT3 is also involved in the regulation of NF-κB signaling in tumor cells and in non-transformed stromal cells in the tumor microenvironment." (PMID 29588647, 2018). "In addition, increased cleaved-caspase-3, an apoptotic marker, and decreased phospho-STAT3 were observed in HepG2 and SK-HEP-1 -driven tumor tissues treated by the combination of emodin and sorafenib." (PMID 30321984, 2018). "We hypothesized that SOCS4 might modulate the JAK/STAT3 and PI3K/AKT pathways, therefore serves as a tumor suppressor downstream of miR-1290 in LADC." (PMID 29552286, 2018). "It is unclear whether STAT3 activation is involved in the acquisition of cancer stem-like cells and EMT-like properties, such as tumor invasion, to modulate the radiosensitivity of GBM." (PMID 30551687, 2018). "The anti-tumor effect of GJXLT might also be related to the inhibition of p-STATS and VEGF expression in the JAK2/STAT3 pathway." (PMID 30271456, 2018). "Other data show that K-ras mutations alter the STAT3 interactome leading to the switch that induces non-canonical STAT3-mediated production of Snail, leading to EMT and tumor progression." (PMID 30081609, 2018). "Targeting STAT3 is therefore an attractive strategy to alleviate MDSC-mediated immunosuppression in the tumor microenvironment without the need for myeloid cell depletion." (PMID 29921770, 2018). "Collectively, these results suggested that tumor‐driven like macrophages secreted IL‐8 via STAT3 pathway to accelerate migration and invasion, not proliferation of PDAC cells." (PMID 30311406, 2018). "STAT3 antagonist JSI-124 suppressed both CD11b+Gr-1− e-MDSCs and conventional CD11b+Gr-1+ MDSCs simultaneously and induced considerable recovery of T cell immunity in vivo and in vitro, thereby displaying more significant anti-tumor efficiency than IL-6R Ab." (PMID 30083161, 2018). "Since STAT3 is a well known downstream effector of IL-6 and TNF-alpha, these data further support the ability of trabectedin to inhibit proinflammatory cytokines secretion from senescent tumor cells." (PMID 29731994, 2018). "Because nuclear accumulation of PKM2 is suggested to be involved in the progression of various tumor, it is a worthy concern that whether inhibition of PKM2 nuclear accumulation is responsible for the suppressed activation of STAT3 by 2-DG in tumor cells." (PMID 29552018, 2018). "Importantly, IL-6 plays key role in promoting tumor progression and immunosuppression, mainly through the downstream activation of JAK/STAT3 signaling." (PMID 29541413, 2018). "Inhibition of STAT3 signaling via adiponectin receptor activation provides a novel approach to inhibit PDAC tumor growth and progression and perhaps enhance therapeutic response to cytotoxic chemotherapy." (PMID 29156726, 2017). "In addition, miR-874 is involved in tumor progression by suppressing the protein levels of MMP-2 and uPA and targeting E2F3, HDAC1, AQP3 STAT3 and HCA587/MAGE-C2 in a variety of cancers." (PMID 28525377, 2017). "In addition, STAT3, as the major effector of IL-6/GP130, is classified as an oncogene contributing to oncogenic transformation in cultured cells and tumor formation in nude mice." (PMID 28672024, 2017). "Most importantly, mice inoculated with STAT3-blocked HCC cells could effectively break tumor-induced immune tolerance, resulting in an effective anti-tumor effect." (PMID 29115974, 2017). "Moreover, the association of TRIM24 with H3K23ac is important for EGFR-stimulated cell proliferation, cell migration, colony formation, tumor growth, GSC self-renewal, p-STAT3, ID1 expression and the binding of TRIM24, H3K23ac and STAT3 with ID1 promoter." (PMID 29129908, 2017).